DDX3X (DEAD-box helicase 3 X-linked)
Description:
Multifunctional ATP-dependent RNA helicase. The ATPase activity can be stimulated by various ribo-and deoxynucleic acids indicative for a relaxed substrate specificity. In vitro can unwind partially double-stranded DNA with a preference for 5'-single-stranded DNA overhangs. Binds RNA G-quadruplex (rG4s) structures, including those located in the 5'-UTR of NRAS mRNA. Involved in many cellular processes, which do not necessarily require its ATPase/helicase catalytic activities (Probable). Involved in transcription regulation. Positively regulates CDKN1A/WAF1/CIP1 transcription in an SP1-dependent manner, hence inhibits cell growth. This function requires its ATPase, but not helicase activity. CDKN1A up-regulation may be cell-type specific. Binds CDH1/E-cadherin promoter and represses its transcription. Potentiates HNF4A-mediated MTTP transcriptional activation; this function requires ATPase, but not helicase activity. Facilitates HNF4A acetylation, possibly catalyzed by CREBBP/EP300, thereby increasing the DNA-binding affinity of HNF4 to its response element. In addition, disrupts the interaction between HNF4 and SHP that forms inactive heterodimers and enhances the formation of active HNF4 homodimers. By promoting HNF4A-induced MTTP expression, may play a role in lipid homeostasis. Associates with mRNPs, predominantly with spliced mRNAs carrying an exon junction complex (EJC). Involved in the regulation of translation initiation. Not involved in the general process of translation, but promotes efficient translation of selected complex mRNAs, containing highly structured 5'-untranslated regions (UTR). This function depends on helicase activity. Might facilitate translation by resolving secondary structures of 5'-UTRs during ribosome scanning. Alternatively, may act prior to 43S ribosomal scanning and promote 43S pre-initiation complex entry to mRNAs exhibiting specific RNA motifs, by performing local remodeling of transcript structures located close to the cap moiety. Independently of its ATPase activity, promotes the assembly of functional 80S ribosomes and disassembles from ribosomes prior to the translation elongation process. Positively regulates the translation of cyclin E1/CCNE1 mRNA and consequently promotes G1/S-phase transition during the cell cycle. Required for endoplasmic reticulum stress-induced ATF4 mRNA translation. Independently of its ATPase/helicase activity, enhances IRES-mediated translation; this activity requires interaction with EIF4E. Independently of its ATPase/helicase activity, has also been shown specifically repress cap-dependent translation, possibly by acting on translation initiation factor EIF4E. Involved in innate immunity, acting as a viral RNA sensor. Binds viral RNAs and promotes the production of type I interferon (IFN-alpha and IFN-beta). Potentiate MAVS/RIGI-mediated induction of IFNB in early stages of infection. Enhances IFNB1 expression via IRF3/IRF7 pathway and participates in NFKB activation in the presence of MAVS and TBK1. Involved in TBK1 and IKBKE-dependent IRF3 activation leading to IFNB induction, acts as a scaffolding adapter that links IKBKE and IRF3 and coordinates their activation. Involved in the TLR7/TLR8 signaling pathway leading to type I interferon induction, including IFNA4 production. In this context, acts as an upstream regulator of IRF7 activation by MAP3K14/NIK and CHUK/IKKA. Stimulates CHUK autophosphorylation and activation following physiological activation of the TLR7 and TLR8 pathways, leading to MAP3K14/CHUK-mediated activatory phosphorylation of IRF7. Also stimulates MAP3K14/CHUK-dependent NF-kappa-B signaling. Negatively regulates TNF-induced IL6 and IL8 expression, via the NF-kappa-B pathway. May act by interacting with RELA/p65 and trapping it in the cytoplasm. May also bind IFNB promoter; the function is independent of IRF3. Involved in both stress and inflammatory responses (By similarity). Independently of its ATPase/helicase activity, required for efficient stress granule assembly through its interaction with EIF4E, hence promotes survival in stressed cells. Independently of its helicase activity, regulates NLRP3 inflammasome assembly through interaction with NLRP3 and hence promotes cell death by pyroptosis during inflammation. This function is independent of helicase activity (By similarity). Therefore DDX3X availability may be used to interpret stress signals and choose between pro-survival stress granules and pyroptotic NLRP3 inflammasomes and serve as a live-or-die checkpoint in stressed cells (By similarity). In association with GSK3A/B, negatively regulates extrinsic apoptotic signaling pathway via death domain receptors, including TNFRSF10B, slowing down the rate of CASP3 activation following death receptor stimulation. Cleavage by caspases may inactivate DDX3X and relieve the inhibition. Independently of its ATPase/helicase activity, allosteric activator of CSNK1E. Stimulates CSNK1E-mediated phosphorylation of DVL2, thereby involved in the positive regulation of Wnt/beta-catenin signaling pathway. Also activates CSNK1A1 and CSNK1D in vitro, but it is uncertain if these targets are physiologically relevant. ATPase and casein kinase-activating functions are mutually exclusive. May be involved in mitotic chromosome segregation. (Microbial infection) Facilitates hepatitis C virus (HCV) replication. During infection, HCV core protein inhibits the interaction between MAVS and DDX3X and therefore impairs MAVS-dependent INFB induction and might recruit DDX3X to HCV replication complex. (Microbial infection) Facilitates HIV-1 replication. Acts as a cofactor for XPO1-mediated nuclear export of HIV-1 Rev RNAs. This function is strongly stimulated in the presence of TBK1 and requires DDX3X ATPase activity. (Microbial infection) Facilitates Zika virus (ZIKV) replication. (Microbial infection) Facilitates Dengue virus (DENV) replication. (Microbial infection) Facilitates Venezuelan equine encephalitis virus (VEEV) replication.
Synonyms: DBX; HLP2; DDX3; DDX14; CAP-Rf; MRX102; MRXSSB
Tractability: Small molecule: a structure with a bound ligand is known; a high-quality ligand is known; it belongs to a druggable protein family. Antibody: UniProt places it where antibodies can reach, with high confidence; its Gene Ontology location is reachable by antibodies, with high confidence. PROTAC: UniProt records ubiquitination sites on it; ubiquitination databases record sites on it; its protein half-life has been measured; a small molecule that binds it is known.
Target class: Enzyme
Gene: Protein-coding gene on chromosome X (41,333,348 to 41,364,472, forward strand). Ensembl gene ENSG00000215301.
Subcellular location: Cell membrane; Nucleus; Cytoplasm; Cytoplasm, Stress granule; Inflammasome; Cell projection, lamellipodium; Cytoplasm, cytoskeleton, microtubule organizing center, centrosome
Subcellular location (Human Protein Atlas): Cytosol; Plasma membrane
Pathways (Reactome):
Disease: Dengue virus activates/modulates innate and adaptive immune responses
Immune System: Neutrophil degranulation
Gene Ontology:
Molecular function: ATP hydrolysis activity; cadherin binding; CTPase activity; DNA binding; DNA helicase activity; eukaryotic initiation factor 4E binding; gamma-tubulin binding; GTPase activity; mRNA 5'-UTR binding; mRNA binding; poly(A) binding; protein binding; protein serine/threonine kinase activator activity; ribonucleoside triphosphate phosphatase activity; ribosomal small subunit binding; RNA binding; RNA helicase activity; RNA stem-loop binding; RNA strand annealing activity; signaling adaptor activity; transcription factor binding; translation initiation factor binding; ATP binding; nucleic acid binding
Biological process: cellular response to arsenic-containing substance; cellular response to osmotic stress; cellular response to virus; chromosome segregation; cytoplasmic pattern recognition receptor signaling pathway; cytosolic ribosome assembly; extrinsic apoptotic signaling pathway via death domain receptors; innate immune response; intracellular signal transduction; intrinsic apoptotic signaling pathway; lipid homeostasis; negative regulation of apoptotic process; negative regulation of cell growth; negative regulation of extrinsic apoptotic signaling pathway via death domain receptors; negative regulation of intrinsic apoptotic signaling pathway; negative regulation of non-canonical NF-kappaB signal transduction; negative regulation of protein-containing complex assembly; negative regulation of translation; positive regulation of apoptotic process; positive regulation of canonical Wnt signaling pathway; positive regulation of cell growth; positive regulation of G1/S transition of mitotic cell cycle; positive regulation of gene expression; positive regulation of interferon-alpha production; positive regulation of interferon-beta production; and 21 more
Cellular component: cell leading edge; centrosome; cytoplasm; cytoplasmic stress granule; cytosol; cytosolic small ribosomal subunit; eukaryotic translation initiation factor 3 complex; extracellular exosome; mitochondrion; nucleus; plasma membrane; canonical inflammasome complex; extracellular region; ficolin-1-rich granule lumen; NLRP3 inflammasome complex; nucleoplasm; P granule; secretory granule lumen; lamellipodium
Gene-disease validity (ClinGen):
ClinGen rates the evidence that DDX3X causes each of these diseases.
X-linked syndromic intellectual disability (X-linked): Definitive. A syndromic intellectual disability with an X-linked mode of inheritance.
Cancer hallmarks: suppression of growth (promotes); escaping programmed cell death (suppresses); invasion and metastasis (suppresses); invasion and metastasis (promotes); change of cellular energetics (promotes)
Homologues: Orthologues: macaque DDX3X (100% identical), pig DDX3X (99% identical), rabbit DDX3X (99% identical), mouse Ddx3x (99% identical), rat Ddx3x (99% identical), chimpanzee DDX3X (97% identical), dog DDX3X (89% identical), tropical clawed frog ddx3x (87% identical), zebrafish ddx3xb (80% identical), zebrafish ddx3xa (79% identical). Paralogues in human: DDX3Y (92% identical), DDX4 (43% identical), DDX17 (33% identical), DDX5 (33% identical), DDX42 (30% identical), DDX46 (29% identical), DDX41 (28% identical), DDX23 (27% identical), DDX43 (27% identical), DDX53 (25% identical), DDX59 (24% identical), DDX21 (24% identical), and 26 more.
Diseases named in the same sentence as DDX3X in open-access papers:
DDX3X is named in the same sentence as 194 diseases in open-access papers, as found by Europe PMC text mining. Sharing a sentence is not in itself a finding about the gene and the disease. The quoted sentences say what the papers report.
breast carcinoma (65 papers, 2011 to 2025). "Although DDX3X has been implicated in breast cancer development, contradictory evidence suggests its role as a tumor suppressor." (PMID 39185415, 2024). "Nevertheless, reduced P21 expression caused by DDX3X overexpression is also observed in breast cancer." (PMID 33627125, 2021). "In breast cancer, DDX3X had been associated with ephitelial-mesenchymal transition, while in gallbladder cancer promote metastasis to lymphatics nodes." (PMID 29899866, 2018). "High DDX3X expression was associated with poor patient prognosis in breast cancer and glioma." (PMID 37988165, 2023). "Indeed, overexpression of the escape genes KDM5C, KDM6A and DDX3X is associated with cancer development, proliferation, invasion and metastasis in certain type of cancers such as breast cancer." (PMID 28686623, 2017). "Consistently, DDX3X also statistically associates with ESR1 in breast cancer." (PMID 26184164, 2015). "Similarly, investigations into DDX3X have highlighted its involvement in splicing defects linked to cancer: DDX3X interacts with splicing factors, modulating alternative splicing of cancer-related genes and facilitating breast cancer adaptation to hypoxia and nutrient deprivation." (PMID 39185415, 2024). "In breast cancer, DDX3X has been found to inhibit the expression of the transcription factor Kruppel-like factor 4 (KLF4)." (PMID 38539466, 2024). "Intriguingly, DDX3X is an RNA-binding protein (RBP) that is associated with a poor prognosis as AEP in both glioblastoma and breast cancer patients." (PMID 38299588, 2024). "The role of DDX3X was investigated in a breast cancer study, where it was found to have an oncogenic role in breast cancer biogenesis." (PMID 38539466, 2024). "A study in 2011 indicated that the overexpression of DDX3X repressed E-cadherin expression in a hypoxia-inducible factor 1 (HIF1)-dependent manner in breast cancer." (PMID 38539466, 2024). "To explore the effect of AEP cleavage of DDX3X on cancer progression, we constructed glioma and breast cancer cells (U87-MG, U251-MG, and MDA-MB-231) with AEP KD as well as with tDDX3X-C rescue (AEP KD/tDDX3X-C res) and verified the lines." (PMID 37988165, 2023). "We then verified the interaction of AEP and DDX3X by endogenous co-IP, especially in glioma (U87-MG and U251-MG) and breast cancer cells (MDA-MB-231) subjected to hypoxia and nutrient deprivation." (PMID 37988165, 2023). "To fully address the effects of AEP cleavage of DDX3X on cancer progression in vivo, we used glioma and breast cancer orthotopic tumor models using NC, AEP KD, and AEP KD/tDDX3X-C res U87-MG or MDA-MB-231 cells." (PMID 37988165, 2023). "In our study, it appeared poorly in BC after 48 h of treatment with E. faecalis, and the aberrant expression of DDX3X has poor clinical outcomes in different cancers, including breast cancer." (PMID 37834385, 2023). "Downregulation of DDX3X promotes stem cell-like properties and tumorigenesis in hepatocellular carcinoma cells, while the upregulation of DDX3 was observed in distant breast cancer metastases and correlated with poor prognosis." (PMID 36937322, 2023). "In breast cancer, DDX3X is overexpressed and acts as an oncogene by promoting proliferation and neoplastic transformation of breast epithelial cells." (PMID 35954483, 2022). "Accordingly, in MCF7 breast cancer cells, the knockdown of DDX3X induces the expression of KLF4, leading to reduced cell growth." (PMID 35954483, 2022). "Specifically, knockdown of DDX3X in breast cancer cell lines decreased their proliferation and clonogenicity in vitro and reduced their ability to generate tumors and form metastases in vivo." (PMID 34638314, 2021). "The expression of DDX3X was found to be correlated with overexpression of HIF-1α in breast cancer, indicating the oncogenic role of DDX3X." (PMID 33393628, 2021).
breast carcinoma (continued). "Human small cell lung carcinoma, colorectal cancer, and breast cancer cells with CSC markers express a high level of DDX3X, yet normal human tissues only faintly express DDX3X." (PMID 33627125, 2021). "Among them, DDX3X has already demonstrated good potential for targeted pharmacological approaches in breast cancer, based on its pro-tumorigenic role in these tumors." (PMID 34638314, 2021). "Mitochondrial localization of DDX3X has been discovered in breast cancer and colorectal cancer cells." (PMID 33627125, 2021). "Inhibition of DDX3X expression or activity reduces proliferation in cells from various tumor tissues, in particular in breast cancer, and its expression often correlates to tumor aggressiveness." (PMID 34638314, 2021). "A series of twelve cancer driver gene expressions were identified to be associated with transcription factors, of which CCR7, BRD7, DDX3X, and UBE2A were upregulated in breast cancer tissues, and the others were downregulated in breast cancer tissues." (PMID 34507558, 2021). "Nonetheless, while DDX3X has a clear pro-tumorigenic role in breast cancer, there are examples of context-dependent pro- or anti-proliferative effects for DDX3X in different or even in the same cancer types." (PMID 34638314, 2021). "Depletion of DDX3X induces G1 phase arrest in breast cancer, lung cancer, colorectal cancer, prostate cancer and medulloblastoma." (PMID 33627125, 2021). "In breast cancer, DDX3X downregulates E-cadherin expression by binding its promoter, and is considered as a potential target for cancer treatment." (PMID 33608512, 2021). "The discovery of DDX3X expression alterations in various cancer types, including hepatocellular carcinoma, breast cancer, colorectal cancer, prostate cancer, and pancreatic cancer, suggests its potential role in modulating tumor behaviors." (PMID 32326089, 2020). "The ectopic overexpression of DDX3X appears to facilitate the tumor progression of breast cancer that is through the activation of the epithelial–mesenchymal transition (EMT) process." (PMID 32326089, 2020). "Similar observations were uncovered in another breast cancer cohort study, in which 35% of the breast cancer patients displayed high DDX3X levels that correlated with poor clinical outcomes." (PMID 31906196, 2019). "In the present work, we show that DDX3X is required for efficient proliferation of MCF7 breast cancer cells and for their progression through the cell cycle, specifically into S phase." (PMID 29782654, 2018). "In order to gain insight into the biological role of DDX3X and investigate the specific requirement of DDX3X function in breast cancer cells, we first analysed the proliferation rates of MCF7 breast epithelial cancer cells upon knockdown of DDX3X." (PMID 29782654, 2018). "Here, we report a mechanism through which DDX3X regulates the cell cycle of breast cancer MCF7 cells." (PMID 29782654, 2018). "Knockdown of DDX3X in MCF7 breast cancer cells induces expression of KLF4, alters KLF4 mRNA exon usage and down‐regulates cell cycle factors genes, CCNA2 and CDK2, leading to reduced cell growth." (PMID 29782654, 2018). "The importance of DDX3X in the proliferation of MCF7 breast cancer cells suggested a relevant and specific biological role for DDX3X in the growth of this cell line." (PMID 29782654, 2018). "We show that DDX3X‐mediated repression of KLF4 promotes expression of S‐phase inducing genes in MCF7 breast cancer cells." (PMID 29782654, 2018). "Here, we demonstrate that DDX3X plays an oncogenic role in breast cancer cells by modulating the cell cycle." (PMID 29782654, 2018). "The DDX3X has tissue specific differential protein production profiles and plays an oncogenic role in human brain glioma, breast cancer, and cervical cancer." (PMID 26184164, 2015). "Overexpression of DDX3X in MCF 10A breast cancer cells prompts an epithelial-mesenchymal-like transformation, increased migration, invasion, and anchorage-independent colony formation." (PMID 26184164, 2015).